TMPRSS2 (transmembrane serine protease 2)
Diseases named in the same sentence as TMPRSS2 in open-access papers (continued):
Sharing a sentence is not in itself a finding about the gene and the disease.
infection (continued). "PD is also predicted to be a potential inhibitor of papain-like proteases in severe acute respiratory syndrome coronavirus 2 (SARS-CoV-2), effectively blocking two main infection pathways of SARS-CoV-2, which are mediated by transmembrane protease serine 2 (TMPRSS2) and lysosome-driven entry." (PMID 40005144, 2025). "No inhibition of infection was observed in any cell line at the highest concentrations of the anti-TMPRSS2 antibody or camostat." (PMID 40749010, 2025). "ACE2 and TMPRSS2 are not only key molecules for SARS‐CoV‐2 to enter host cells, but also important auxiliary proteins that mediate other coronaviruses (such as SARS‐CoV) infection." (PMID 40145441, 2025). "Alternatively, an apparent incomplete block of infection by ACE2 antibody and TMPRSS2 inhibitor might be a consequence of cell-to-cell spread of virus that occurred after inhibitors were removed from the culture media." (PMID 40445428, 2025). "The virus can enter cells through cathepsin-mediated endocytosis without TMPRSS2 involvement, and there is evidence that infection can be mediated through other factors such as GRP78, a binding partner to ACE2 and phosphatidylserine receptor mechanisms." (PMID 41157583, 2025). "We speculate that the chalcone-mediated inhibition of viral entry is not likely because all four viruses tested here bind to different cellular receptors to initiate the infection: sialic acid for PIV5, DC-SIGN for LACV, AXL for ZIKV, and TMPRSS2 for OC43." (PMID 41008592, 2025). "Lastly, for the cell entry genes ACE2 and TMPRSS2 (as the receptor of the SARS-CoV-2 cell entry mechanism), we observed a significant decrease in expression; they were highly expressed during early infection (0 hpi) and constantly decreased during the late-phase infection." (PMID 40649996, 2025). "Furthermore, the existence of particulate matter can trigger the activation of transmembrane serine protease 2 (TMPRSS2) and angiotensin-converting enzyme 2 (ACE-2), leading to an increase in the number of SARS-CoV-2 binding sites and infection efficiency." (PMID 41223235, 2025). "Such infection appears to be poorly correlated with levels of ACE2, TMPRSS2, or NRP1 expression." (PMID 40674406, 2025). "This enhancement of infection, which was more pronounced in ACE2/TMPRSS2 target cells, may be due to sub-stoichiometric or incomplete inhibition of all spikes required for a fusion pore." (PMID 40198676, 2025). "We infected Vero-TMPRSS2 and A549-ACE2 cells at an MOI of 0.01 with Wuhan-Hu-1 (ancestral) and mutant viruses, and measured mCherry fluorescence as well as viral release into the supernatant at indicated time points post-infection." (PMID 40568176, 2025). "Since P selectin can antagonize both pseudovirus and authentic infection of ACE2-expressing cells, we hypothesized that it would also block infection of ACE2/TMPRSS2+ HEK293 target cells." (PMID 41243963, 2025). "Regarding males, it has been observed that the infection tends to be acute when there is high expression of ACE2 and TMPRSS2 in the testes, inducing inflammatory and hypoxic processes that interfere with testosterone production and alter the permeability of the blood-testis barrier." (PMID 41416316, 2025). "However, infection fully overlaps in regions where ACE2 and TMPRSS2 co-localize, specifically in the tertiary bronchi, bronchioles, and alveoli." (PMID 39858469, 2025). "We then performed single-cycle infection experiments with pH-treated BavPat1 samples on Vero-E6 cells overexpressing ACE2 and TMPRSS2 (VAT cells), and tested for the production of nucleocapsid (N) protein by immunofluorescent (IF) staining 7 h post-infection (hpi)." (PMID 40691508, 2025). "Given that HS is required for Omicron infection of ACE2 low-expressing cells, these results suggest that TMPRSS2-mediated cleavage of HSPGs may contribute to the reduced infectivity of the Omicron variant to TMPRSS2-expressing cells." (PMID 40548749, 2025).
infection (continued). "Furthermore, the partial reduction of infection in cells endogenously expressing both DPP4 and TMPRSS2 following treatment with a TMPRSS2 inhibitor, in contrast to the lack of inhibition in cells expressing only DPP4, confirms the dual entry path of MERS-CoV." (PMID 40295839, 2024). "These seem to make the oral mucosae unfavorable primary targets for infection by SARS-CoV-2 as far as ACE2-furin-TMPRSS2 pathway entry is regarded, irrespective of the normal/inflammatory/dysplastic/neoplastic status of the lining epithelial cells." (PMID 38489333, 2024). "Previous study suggested that the placenta at term expressed ACE2 moderately but not TMPRSS2, so they believed that transplacental transmission rarely occurred at term but raised concern about preterm infection." (PMID 38233605, 2024). "Consistently, the S813V mutant also showed significantly higher titer than WT at 24 h post-infection (hpi) in Vero cells (p = 0.01), but not in Vero-TMPRSS2 cells." (PMID 38744813, 2024). "Unlike Delta infection, Omicron infection has been shown to result in an increased dependence on cathepsin B instead of on transmembrane serine protease 2 (TMPRSS2)." (PMID 38201428, 2024). "Cathepsins are upregulated upon infection, which contributes to aggravating infection, especially in those tissues where other proteases, such as TMPRSS2, are not as present, thus allowing a new entry route to infect these cells." (PMID 39062796, 2024). "CRFK-derived EVs at the 48 h and 72 h infection time points contained significant levels of ACE2 and TMPRSS2, which may confirm that infected EVs serve an important function in assisting the dissemination of CoV and extracellular virus production in the host." (PMID 39091390, 2024). "It seems reasonable to speculate and open for discussion the possibility that the infection of other projection neurons throughout the brain was associated with the expression of other proteins used by the virus as entry receptors that are independent of ACE2 or TMPRSS2." (PMID 38834299, 2024). "They measured the infection inhibition on cellular models (i.e., Calu3 and VeroE6 cells) combined with LC/MS analyses, and they found some extracts that inhibited SARS-CoV-2 infection in a TMPRSS2-dependent manner." (PMID 37375781, 2023). "Conversely, when the SARS-CoV-2 interacts with the TMPRSS2-lacking cells, the virus uses the endocytosis pathway, which takes about 40–60 min to complete upon infection." (PMID 36124445, 2023). "Another recent study showed that omicron infection is not triggered or enhanced by transmembrane serine protease 2 (TMPRSS2); instead, the enhancement is primarily mediated by endocytic pathways." (PMID 36976007, 2023). "As anticipated, both trypsin treatment and TMPRSS2 expression significantly enhanced the infection of HCoV-229Epp, but not VSVpp, in Huh7- and fAPN-expressing 293T cells." (PMID 37676001, 2023). "The results shown here could provide a route for endothelial cell infection in vivo by SARS-CoV-2 despite normally low ACE2 and TMPRSS2 levels." (PMID 36408607, 2023). "Besides ACE2, the most prominent receptor, other receptors that mediate CoV2 infection of human cells include neuropilin-1 (NRP1), Eph receptors, transmembrane serine protease 2 (TMPRSS2), P2X7, and CD147 (BSG)." (PMID 38203569, 2023). "We therefore observed a more proinflammatory reaction to infection simulation with RNA or unmethylated CpG sequences in cDC cultures in the absence of functional TMPRSS2." (PMID 36830955, 2023). "Moreover, other crucial proteins for the infection and spread of SARS-CoV-2 in the CNS have also been identified, including NRP1, transmembrane protease serine 2 (TMPRSS2), basigin, and cathepsin L." (PMID 36998270, 2023). "In this regard, we did not observe any adverse effect of stable TMPRSS2 expression in AKAV replication or infection with lentiviral vectors." (PMID 38251326, 2023).
infection (continued). "Here, we elucidate the role of TMPRSS2 non-protease domains in regulating SARS-CoV-2 lenti-Spike infection." (PMID 37896901, 2023). "In detail, transgenic A549-lung cells engineered to express ACE2 and TMPRSS2, control lysates of Caco-2 cells 48 hpi with SARS-CoV-2, and most importantly we checked the permissivity of our ex vivo cell culture system for infection per se validated by infection with HCMV." (PMID 35920896, 2023). "This suggests that pigTMPRSS2 expression does not affect virus replication and infection of TMPRSS2-independent viruses." (PMID 38251326, 2023). "Additionally, the study aimed to elucidate the interplay between microRNAs and the ACE2 and TMPRSS2 proteins, which play crucial roles in facilitating SARS-CoV-2 viral entry and infection." (PMID 38444707, 2023). "We expanded our investigation beyond TMPRSS2 CT and discovered the involvement of other non-protease domains in regulating infection." (PMID 37896901, 2023). "Our previous work showed that infection by SARS-CoV-2 could be attenuated by treatment with AR or BET inhibitors, which decreased expression of the critical host entry factors ACE2 and TMPRSS2." (PMID 36735698, 2023). "This fact could be explained by the role of further surface molecules and proteases in SARS-CoV-2 cell infection, limiting the value of ACE2 and TMPRSS2 as standalone markers." (PMID 36453030, 2023). "Different expression patterns of TMPRSS2 and TMPRSS4 in bat airway organoids might affect the infection of different bat species." (PMID 36916937, 2023). "In this study, we have chosen to use relevant models for SARS-CoV-2 infection, i.e., not requiring ACE2 transduction and whose infection mainly occurs via the TMPRSS2-dependent pathway." (PMID 36834705, 2023). "The fact that TMPRSS2 expression is low does not lead to an automatic decrease in the possibility of infection." (PMID 38255667, 2023). "Exposure to SARS-CoV-2 did not affect the expression of ACE2 and TMPRSS2, and, despite the apparent lack of productive infection, exposure to SARS-CoV-2 increased cleaved caspase-3 immunoreactivity, an indicator of apoptotic cell death." (PMID 36992454, 2023). "In TMPRSS2-negative cells, infection of both lenti-Delta and lenti-Omicron Spike was inhibited by E64d and imatinib, but not by camostat, verifying their endosomal route." (PMID 37243215, 2023). "Once in the brain, utilization of the endosomal pathway by omicron viruses (and original ancestral isolates with non-functional furin cleavage sites) allows a spreading infection in TMPRSS2-low brain cells (Brains)." (PMID 38075874, 2023). "Next, we investigated TMPRSS2 dependency in infection and found that TMPRSS2 did not improve the infection of wt Omicron or the Omicron Spike F375S mutant." (PMID 37243215, 2023). "These increases in infection may be due to higher ACE2 expression and elevated TMPRSS2 activities in the nicotine-treated BEAS-2B cells, than in the PG/VG and JUUL groups." (PMID 37037851, 2023). "Infection was successfully mitigated by endocytosis inhibitors, such as Dyngo4a, but was not affected by TMPRSS2 inhibitors, supporting the conclusion that SARS-CoV-2 virus entered Mv1Lu cells mainly by endocytosis." (PMID 38033586, 2023). "This is in agreement with previous in vitro reports, which found productive infection with SARS-CoV-2 of hPSC-derived ChP organoids, and hiPSC-derived ChP epithelial cell aggregates, as well as by the fact that ChP epithelia express ACE2 and TMPRSS2 in situ." (PMID 37875964, 2023). "Novel inhibitors have been developed against TMPRSS2-mediated spike activation at the plasma membrane and have been shown to be effective against SARS-CoV-2 entry in both human lung epithelial cells and murine infection models." (PMID 36992348, 2023). "However, in vitro infection of VeroE6 cells expressing ACE2 and TMPRSS2 with lung homogenate from intracranially infected mice resulted in cytopathic effect, indicating the presence of infectious virus." (PMID 37790412, 2023).
infection (continued). "By comparing other SPs in parallel and using dose gradients, we confirmed that furin, TMPRSS2, and trypsin facilitate—rather than impede—infection." (PMID 37024459, 2023). "In a separate study, the overexpression of IFITM3 did not restrict but enhanced the spike-mediated infection in TMPRSS2-expressing cells, suggesting that altered usage of host protease or fusion at the plasma membrane subverts the effect of host IFITMs." (PMID 36992348, 2023). "Infection tests on Huh-7 cells, expressing or not the cellular protease TMPRSS2, using luciferase reporter virus HCoV-229E-Luc showed that luteolin exhibited a dose-dependent inhibition of infection." (PMID 37298740, 2023). "Increases in infection were not always associated with increases in ACE2 and TMPRSS2 (e.g., in the JUUL Cultex group)." (PMID 37037851, 2023). "Original data suggest that the downregulation of TMPRSS2 and/or ACE2 expression on the cell surface could avert viral entry into the host cell and, consequently, infection spreading." (PMID 37324739, 2023). "The productive infection was ACE2 dependent and TMPRSS2 independent." (PMID 37039676, 2023). "BHH completely inhibited the infection of authentic SARS-CoV-2 in TMPRSS2-negative cells, and was only slightly active in TMPRSS2-expressing lung cells." (PMID 35163273, 2022). "Transmembrane protease serine 2 (TMPRSS2) and mosaic serine protease large-form (MSPL) have the characteristics of promoting PEDV S protein cleavage, promoting cell–cell fusion and virus–cell fusion during PEDV infection." (PMID 36298772, 2022). "In the absence of TMPRSS2, lenti-Spike infection of HEK293T-hACE2 was robustly inhibited with both E64d and imatinib but not camostat." (PMID 35388061, 2022). "The difference in susceptibility to SARS-CoV-2 infection between Vero-ACE2-TMPRSS2 and Vero-TMPRSS2 persisted up to 7 days after infection (data not shown)." (PMID 35834347, 2022). "The amount of ACE2 in the tissues has not shown a correlation with infection or with TMPRSS2 in any of the reported organs." (PMID 35672403, 2022). "Moreover, EVs containing ACE2, alone or in combination with transmembrane protease serine 2 (TMPRSS2), from transfected 293FT mock cell, block SARS-CoV-2 spike-dependent infection in a much more efficient manner than soluble ACE2." (PMID 35011708, 2022). "In the absence of TMPRSS2, imatinib was as potent as the cathepsin L inhibitor (E64d) in blocking lenti-Spike infection, suggesting that imatinib inhibits infection in endosomal pathway." (PMID 35388061, 2022). "It is important to note that this work was carried out in vitro and specifically in an ACE2-transfected HEK293T cell line, which lacks the SARS-CoV-2 co-receptor TMPRSS2, so does not mimic the prominent viral entry mechanism seen in natural infection." (PMID 35444667, 2022). "The transmembrane protease serine 2 (TMPRSS2) also plays a relevant role in cell infection by participating in membrane fusion and internalization of the spike-ACE2 complex, essential for host cell infection." (PMID 35203711, 2022). "These microRNAs could regulate the translation of the TMPRSS2 protease with important effects on the S protein priming of the SARS-CoV-2 and, in consequence, in the process of infection by this virus." (PMID 36146782, 2022). "Chloroquine has been shown to inhibit SARS-CoV-2 infection in the absence of TMPRSS2 but have less effect on infection in the presence of TMPRSS2." (PMID 36298757, 2022). "Targeting TMPRSS2 is a promising antiviral strategy because the protease is not only essential for SARS-CoV-2 entry, but also primes glycoproteins of various other viruses for subsequent fusion and infection." (PMID 35804152, 2022). "Additionally, the authors showed that, in particular, adalimumab increases the TMPRSS2/ADAM17 ratio, suggesting the infection facilitated by TMPRSS2." (PMID 35631442, 2022).
infection (continued). "The AXL-specific inhibitor bemcentinib inhibits SARS-CoV-2 infection in various lung cell lines, including some with low ACE2 but does not inhibit infection of Calu-3 cells, which express high levels of TMPRSS2." (PMID 36423144, 2022). "Junquira’s group observed that LPS did not induce ACE2 expression in monocytes and that blocking ACE2 and TMPRSS2 did not diminish monocyte infection, which was FcγR dependent." (PMID 36085197, 2022). "SARS-CoV-2 negative placentae showed elevated levels of CD147 and considerably low amount of TMPRSS2, making them non-permissive to infection." (PMID 36177036, 2022). "For an in vivo human or animal infection, the virus will encounter and potentially infect a number of cell types, some lacking TMPRSS2 expression." (PMID 36293378, 2022). "The observed augmentation in infection with Omicron was serum dose-dependent and required ACE2, because the parental cell line (K-ML2, lacking ACE2 and TMPRSS2) of clone 35 exhibited no infection with Omicron even in the presence of serum." (PMID 36114224, 2022). "The infection of both SARS-CoV and SARS-CoV-2 is initiated by the attachment of the S protein to the host receptor angiotensin-converting enzyme 2 (ACE2), followed by the S protein priming by cellular proteases such as TMPRSS2." (PMID 35572668, 2022). "Infection of human peripheral blood cells by SARS-CoV-2 has been debated because immune cells lack mRNA expression of both angiotensin-converting enzyme 2 (ACE2) and transmembrane serine protease type 2 (TMPRSS2)." (PMID 36085197, 2022). "Therefore, topical TMPRSS2 inhibition when delivered in a clinically relevant and achievable dose to differentiated airways cells markedly restricts SARC-CoV-2 cellular infection." (PMID 35110354, 2022). "SARS-CoV-2 initiates its infection process via interaction with the human angiotensin-converting enzyme 2 (ACE2) receptors through its receptor-binding domain (RBD), and uses the transmembrane protease serine 2 (TMPRSS2) for priming the spike protein." (PMID 35889352, 2022). "The infection is initiated by the attachment of the virus (spike) S protein to the host cellular entry receptor angiotensin converting enzyme 2 (ACE2), and other virus entry co-factors, such as transmembrane serine protease 2 (TMPRSS2)." (PMID 35056429, 2022). "Cofactor facilitating SARS-CoV-2 infectivity such as TMPRSS2 cleaves the spike (S) protein of SARS-CoV-2 and facilitates the fusion of SARS-CoV-2 and cellular membranes, thus a critical factor enabling cellular infection." (PMID 35160229, 2022). "In crypts, which are less exposed, no significant change in TMPRSS2 expression was observed during infection compared to pre infection time points (pre: 7.35 ± 0.90%; acute: 5.78 ± 0.73; and chronic: 8.14 ± 0.56)." (PMID 35281029, 2022). "We hypothesize that infection only occurs where ACE2 and TMPRSS2 are both present in sufficient density." (PMID 35255100, 2022). "The infection of host cells by SARS-CoV-2 requires the presence of transmembrane receptor Angiotensin-Converting Enzyme 2 (ACE2) and Type II Transmembrane Serine Protease (TMPRSS2)." (PMID 36177036, 2022). "Furthermore, CNTN1 expression also increased infection in the presence of ACE2 and TMPRSS2, relative to ACE2 and TMPRSS2 alone." (PMID 35931765, 2022). "Similar, or greater, levels of expression of ACE2 and TMPRSS2 were observed in this donor, confirming that resistance to infection was not due to absence or low expression of the attachment and entry factors needed for SARS-CoV-2 infection." (PMID 35436306, 2022). "A limitation of Vero cells as recipients is that mostly CTSL but not TMPRSS2 mediates spike processing unlike in vivo infection of human lung cells with SARS-CoV-2." (PMID 36382127, 2022).